MAP2K1 (mitogen-activated protein kinase kinase 1)
Diseases named in the same sentence as MAP2K1 in open-access papers (continued):
Sharing a sentence is not in itself a finding about the gene and the disease.
Hearing impairment (2 papers, 2023 to 2024). A decreased magnitude of the sensory perception of sound. "Furthermore, eczema (p = 0.07), hearing impairment (p = 0.07), cryptorchidism (p = 0.13), and pulmonary valve stenosis (p = 0.19) were commonly found in patients with MAP2K1/2 variants, while macrocephaly (p = 0.13) was often observed in patients with BRAF variants." (PMID 37697378, 2023).
hemangioma (2 papers, 2021 to 2022). A benign vascular lesion characterized by the formation of capillary-sized or cavernous vascular channels. "Most of other MAPK family members were downregulated for both involuting and proliferating hemangioma except MAP2K1 which was found to be upregulated for both types of our hemangioma." (PMID 35740845, 2022).
Hyperglycemia (2 papers, 2018 to 2019). An increased concentration of glucose in the blood. "Among these genes was the mitogen-activated protein kinase kinase 1 (MAP2K1), a key molecule in the ERK1/2 MAP kinase pathway, with 1.7-fold (p = 5.37 × 10−9) upregulated under euglycemia-CoCl2, and 1.6-fold (p = 6.8 × 10−8) upregulated under hyperglycemia-CoCl2." (PMID 29351188, 2018).
injury (2 papers, 2011 to 2025). Damage inflicted on the body as the direct or indirect result of an external force, with or without disruption of structural continuity. "Additionally, we observed significant activation of MAP2K1 in the M-type, which, according to previous literature, may regulate pulmonary macrophage inflammatory responses and resolution of acute lung injury." (PMID 39950116, 2025).
Intellectual disability (2 papers, 2023 to 2025). "MAP2K1 variants are correlated with skeletal deformities and motor dysfunction, and MAP2K2 and KRAS variants are correlated with mild intellectual disability." (PMID 37697378, 2023). "Specifically, in terms of neurodevelopmental functions, patients with mutations in the MAP2K2 gene show a lower incidence of intellectual disability (ID) compared to those with mutations in other genes, such as BRAF and MAP2K1, with an incidence rate of only 25%." (PMID 39982946, 2025).
ovarian tumor (2 papers, 2021 to 2023). "Previous studies have identified that the miR-34c and the miR-320 act as regulatory molecules of insulin-producing in mesenchymal stem cells or cell proliferation in ovarian tumor cells via targeting to MAPK1 or MAP2K1, respectively." (PMID 38174044, 2023).
Parkinson disease (2 papers, 2023 to 2024). A progressive degenerative disorder of the central nervous system characterized by loss of dopamine producing neurons in the substantia nigra and the presence of Lewy bodies in the substantia nigra and locus coeruleus. "The authors showed a role for inflammatory astrocytes in BBB leakage observed in Parkinson’s disease, which was attenuated by inhibition of mitogen-activated protein kinase kinase 1/2 (MEK1/2) signaling." (PMID 38008744, 2023).
rectal cancer (2 papers, 2017 to 2025). A primary or metastatic malignant neoplasm that affects the rectum. "Variation among genes in the MAPK pathway predisposes to colon and rectal cancer, including susceptibility variants in MAP2K1." (PMID 28333948, 2017). "We observed that inhibitors of the RAS-MAPK pathway, in particular mitogen-activated protein kinase kinase 1/2 (MEK1/2) inhibitors, can strongly increase the sensitivity of rectal cancer organoids and CRC cell lines to radiation." (PMID 40782795, 2025).
respiratory infections (2 papers, 2024 to 2025). "One potential therapeutic strategy to combat respiratory infections and inflammation has been developed from understanding the functional roles of mammalian serine threonine protein kinases Map2k1 (MEK1) and Map2k2 (MEK2)." (PMID 40422262, 2025).
Salmonella Infections (2 papers, 2023). Infections with bacteria of the genus SALMONELLA. "Contrary to our expectation, Salmonella infection was also enriched in clusters 1 and 3, and thus, we reviewed the DEGs and found that only six DEGs, such as AHNAK, MAP2K1, MAPK10, ARL8B, IL6, and PFN2, were enriched after S. enterica BNCC186354 infection, but only ARL8B and PFN2 were downregulated." (PMID 36980306, 2023).
Spitz nevi (2 papers, 2021 to 2024). "MAP2K1 mutations can be observed in the whole spectrum of Spitz tumors, ranging from Spitz nevi (SN) to Spitz melanoma (SM), while MAP2K1-activating in-frame deletions have been detected in Spitz melanocytomas with dense pigmentation and mostly indolent clinical course." (PMID 38397186, 2024). "We could not discern a clearly distinct phenotype within these MAP2K1-mutated lesions, although two cases resembled desmoplastic Spitz nevi." (PMID 33040161, 2021).
squamous cell lung carcinoma (2 papers, 2016 to 2023). A carcinoma arising from squamous bronchial epithelial cells. "The squamous cell lung carcinomas showed two cases with ARID1A loss of function variants (E1718* and G1848fs), one FGFR3 S249C variant, one MAP2K1 P124L, and one case with PIK3CA amplification and E545A variant." (PMID 36125633, 2023).
ZIKV infection (2 papers, 2017 to 2026). "The inflammatory profile is partially different following ZIKV infection, which is mainly characterized by less inflammatory response and by the specific induction of several MAPK genes (MAP2K1, MAP2K3, MAP3K7, MAPK1, MAPK3)." (PMID 28873445, 2017).
acute kidney injury (1 paper, 2024). Sudden and sustained deterioration of the kidney function characterized by decreased glomerular filtration rate, increased serum creatinine or oliguria. "This study evaluated the protective effects of trametinib, an FDA-approved selective inhibitor of mitogen-activated protein kinase kinase 1/2 (MEK1/2), against cisplatin-induced acute kidney injury (AKI) in mice." (PMID 38930946, 2024).
acute lung injury (1 paper, 2025). A condition of lung damage that is characterized by bilateral pulmonary infiltrates (pulmonary edema) rich in neutrophils, and in the absence of clinical heart failure. "MAP2K1 and MAP2K2, integral to the MAPK/ERK signaling pathway, have been shown to regulate inflammation and interferon responses, with MAP2K2 deactivation promoting the resolution of acute lung injury (ALI)." (PMID 40703672, 2025).
age-related hearing loss (1 paper, 2022). "Although Map2k1 has not been directly implicated in age-related hearing loss, MAP kinases, in general, integrate multiple cellular signaling pathways biochemical signals and are, therefore, poised to interrelate various biological processes involved in age-related hearing loss." (PMID 35454087, 2022).
amyotrophic lateral sclerosis (1 paper, 2025). Amyotrophic lateral sclerosis (ALS) is a neurodegenerative disease characterized by progressive muscular paralysis reflecting degeneration of motor neurons in the primary motor cortex, corticospinal tracts, brainstem and spinal cord. "RAD23B is involved in DNA repair and neurodegeneration in neurodegenerative diseases such as amyotrophic lateral sclerosis, while MAP2K1 plays a critical role in synaptic plasticity and neurotransmission in addiction and psychiatric disorders." (PMID 40438583, 2025).
bile duct tumor (1 paper, 2025). "Single-cell RNA-seq mapping of FLNC, MAP2K1, and ABCA1 reveals highly specific, lineage-restricted transcriptional programs within the bile duct tumor microenvironment." (PMID 41373405, 2025).
bleeding disorders (1 paper, 2021). "The mutational spectrum of patients with bleeding disorders was largely overlapping with that of the NS general population, including mutations in PTPN11, SOS1, RIT1, BRAF, and MAP2K1 genes." (PMID 34857025, 2021).
breast invasive carcinoma (1 paper, 2021). "In particular, a statistically significant association was found between CHEK1, MAP2K1, and PLK1 overexpression and worse overall survival in breast invasive carcinoma patients, indicated by pooled hazard ratio (HR) values higher than 1 and p-values lower than 0.05." (PMID 33898418, 2021).
congenital vascular malformation (1 paper, 2019). A congenital abnormality of the arteries and veins, lymph vessels or veins and lymph vessels. "Several somatic mutations in MAPK related genes, such as MAP kinase kinase 1 (MAP2K1 or MEK1), MAP kinase kinase kinase 3 (MAP3K3, or MEKK3), EPHB4 and TEK, have been found in congenital vascular malformations." (PMID 31067686, 2019).
cutaneous squamous cell carcinoma (1 paper, 2024). "Concomitant alterations in the MAP2K1 and FGFR3 genes, as it is in the present case, have been described in cases of cutaneous squamous cell carcinoma that presented a significant response to EGFR inhibitors (cetuximab)." (PMID 39273494, 2024).
endothelial dysfunction (1 paper, 2021). In vascular diseases, endothelial dysfunction is a systemic pathological state of the endothelium (the inner lining of blood vessels) and can be broadly defined as an imbalance between vasodilating and vasoconstricting substances produced by (or acting on) the endothelium. "A somatic activating mutation in the MAP2K1 gene causing endothelial dysfunction via increased MEK1 activity has been proposed." (PMID 33816543, 2021). "It has been proposed that AVM results from a vascular developmental error during embryogenesis, namely a somatic activating mutation in the MAP2K1 gene causing endothelial dysfunction through increased MEK1 activity." (PMID 33816543, 2021).
esophageal adenocarcinoma (1 paper, 2019). A malignant tumor with glandular differentiation arising predominantly from Barrett mucosa in the lower third of the esophagus. "Use case – Esophageal adenocarcinoma with reported amplification ofCCND1,MAP2K1,RICTOR,FGF10,FGF19,FGF3,FGF4 andMCL1." (PMID 31608148, 2019).
gallbladder adenocarcinoma (1 paper, 2022). A carcinoma that arises from glandular epithelial cells of the gall bladder. "In the CCA cohort, another driver MAP2K1 mutation occurred in a case of gallbladder adenocarcinoma (p.G128D)." (PMID 36013219, 2022). "Interestingly, one gain of function oncogenic mutation in the MAP2K1 gene could be found in a CCA cell line (p.K57T, negative regulatory domain) and in a case of gallbladder adenocarcinoma (p.G128D, kinase domain)." (PMID 36013219, 2022).
Hepatitis B (1 paper, 2021). "The key target genes enriched in the Hepatitis B pathway include MAP2K1 and CASP8." (PMID 33863948, 2021).
histiocytic sarcoma (1 paper, 2021). An aggressive malignant neoplasm with a poor response to therapy, usually presenting as stage III/IV disease. "Recently, a histiocytic sarcoma patient with a MAP2K1 F53L mutation received the MEK inhibitor trametinib and showed a rapid and durable complete response for more than 2 years." (PMID 34356494, 2021).
HIV-1 infection (1 paper, 2018). The type species of lentivirus and the etiologic agent of acquired immunodeficiency syndrome (AIDS). "Together, these results reveal a unique example of pathogenic control over mammalian apoptosis and DNA damage via a host long noncoding RNA, and present MAP2K1/ERK2 inhibitors as a novel therapeutic intervention strategy for HIV-1 infection in macrophages." (PMID 30123777, 2018). "Together, these observations revealed that HIV-1 infection specifically increases MAP2K1 expression, and strongly suggested that HIV-1 can counteract lincRNA-p21 mediated suppression of MAP2K1." (PMID 30123777, 2018).
hyperuricemia (1 paper, 2026). An abnormally high level of uric acid. "Additionally, MAP2K1 regulates the HIF‐1α signaling pathway, while hyperuricemia activates the ERK pathway, further impacting HIF‐1α." (PMID 41561638, 2026).
hypogammaglobulinemia (1 paper, 2025). "Genotype-phenotype analysis revealed that BRAF mutations were predominantly associated with T-cell lymphopenia, whereas MAP2K1 mutations were linked to monocytosis, reduced naïve and switched-memory B cells, and hypogammaglobulinemia." (PMID 40692796, 2025). "Recently, case reports have described the immunological phenotype of CFCS, reporting antibody deficiency in patients affected by MAP2K1 and MAP2K2 mutations." (PMID 40692796, 2025).
hypothyroidism (1 paper, 2020). Abnormally low levels of thyroid hormone. "At a gene level, PTPN11, NRAS, RASA2, SOS2, MAP2K1, and RAF1 were significantly associated with hypothyroidism, diastolic and systolic BP, birth weight, growth abnormality, subcutaneous adipose tissue, standing/sitting height ratio and body mass index." (PMID 33226994, 2020).
intracranial AVM (1 paper, 2019). "Also, although we previously reported that MAP2K1 mutations are a common cause of extracranial AVM, we did not observe MAP2K1 mutations in any of our intracranial AVM specimens." (PMID 31891627, 2019).
leukocytosis (1 paper, 2025). "In the CBC, leukocytosis was observed more frequently in patients with MAP2K1 (33.3%) compared to BRAF mutations (14.3%)." (PMID 40692796, 2025).
lymphopenia (1 paper, 2025). Reduction in the number of lymphocytes. "Similarly, CD8+ lymphopenia was more frequent in BRAF-mutated patients (31.0%) compared to MAP2K1 (9.1%)." (PMID 40692796, 2025). "Similarly, lymphocytosis was more common in the MAP2K1 cohort (16.7%) compared to BRAF (3.1%), while lymphopenia was higher in BRAF-mutated patients (25.0%) than in MAP2K1-mutated patients (8.3%)." (PMID 40692796, 2025). "Regarding lymphocyte subsets, CD4+ lymphopenia was observed in 34.5% of patients with BRAF mutations, whereas only 9.1% of MAP2K1-mutated individuals exhibited this finding." (PMID 40692796, 2025).
Myocardial fibrosis (1 paper, 2023). "Myricetin can also upregulate the expression levels of Egfr and Map2k1, which regulate the biological process of myocardial phosphorylation, producing a protective effect by reducing the myocardial inflammatory response and slowing myocardial fibrosis." (PMID 36986067, 2023).
omphalocele (1 paper, 2020). Omphalocele is an embryopathy classified in the group of abdominal celosomias and is characterized by a large hernia of the abdominal wall, centered on the umbilical cord, in which the protruding viscera are protected by a sac. "Similarly, inactivating Mek1 (also known as Map2k1) in a Mek2 (Map2k2) null background with a mesenchyme-specific Cre resulted in omphalocele." (PMID 32907848, 2020).
primary cardiomyopathy (1 paper, 2023). "Therefore, we ultimately identified four genes as differential CRGs shared by the three kinds of primary cardiomyopathy: COA6, FDX1, MAP2K1, and SLC31A1." (PMID 38085668, 2023). "The mRNA and protein levels of FDX1, MAP2K1 and SLC31A1 were significantly down-regulated during cuproptosis in cardiomyocytes, which was in line with the expression trends of the three kinds of primary cardiomyopathy groups in the GEO datasets." (PMID 38085668, 2023).
primary immunodeficiency (1 paper, 2024). "GSEA revealed that MAP2K1 is predominantly associated with the metabolism of xenobiotics by cytochrome P450, primary immunodeficiency and tyrosine metabolism." (PMID 39835132, 2024).
reactive disorder (1 paper, 2025). "Recent studies have shown that approximately one-third of patients with RDD harbor mutations in genes involved in the MAPK/ERK pathway, such as NRAS, KRAS, MAP2K1, and, rarely, BRAF, indicating a neoplastic process rather than a reactive disorder." (PMID 40385897, 2025).
renal carcinoma (1 paper, 2020). A carcinoma arising from the epithelium of the renal parenchyma or the renal pelvis. "As a tumor suppressor in bladder and renal cancers, VEGFC, CTNNB1, and MAP2K1 were three targets of miR-1826 to mediate its inhibiting effect on tumorigenesis." (PMID 32104674, 2020).
Respiratory tract infection (1 paper, 2025). An infection of the upper or lower respiratory tract. "Immunoglobulin replacement therapy (IgRT) was initiated in three individuals, all of whom carried MAP2K1 variants, had decreased IgG levels and a history of recurrent respiratory tract infections." (PMID 40692796, 2025).
scoliosis (1 paper, 2021). A congenital or acquired spinal deformity characterized by lateral curvature of the spine. "On the same way, our study documents that patients with CFCS harboring the MAP2K1/2 pathogenic variants generally show a more severe skeletal phenotype compared to other CFCS patients, with a higher prevalence of scoliosis and multiple joint contractures." (PMID 33482860, 2021). "In the CFCS group, patients with MAP2K1/2 pathogenic variants showed different skeletal characteristics compared to those carrying BRAF variants, with a higher prevalence of scoliosis, pectus anomalies, upper limbs anomalies, hip contractures and pes valgus compared to the BRAF variant." (PMID 33482860, 2021).
steatosis (1 paper, 2025). Increased lipid within the cytoplasm of cells. "Furthermore, concentration‐dependent inhibition of steatosis and fibrosis was replicated for selumetinib (MAP2K1 inhibitor), MK‐2206 (AKT inhibitor), and PF‐05105679 (TRPM8 inhibitor)." (PMID 39605182, 2025).
systemic lupus erythematosus (1 paper, 2020). An autoimmune multi-organ disease typically associated with vasculopathy and autoantibody production. "In the third trimester, systemic lupus erythematosus and proteasome were enriched in the acute disease while Fc gamma R-mediated phagocytosis (VAV1, MARCKSL1, WASF2, DNM2, HCK, MAP2K1 genes) and adherens junction (ACTG1, WASF2, SMAD4, CSNK2B, EP300 genes) represented the subclinical category." (PMID 32012176, 2020).
vitiligo (1 paper, 2025). Generalized well circumscribed patches of leukoderma that are generally distributed over symmetric body locations and is due to autoimmune destruction of melanocytes. "Finally, we obtained ten matched genes (GP1BA, ANKS4B, CCDC87, CA8, HLA‐DOB, RHEBL1, NLRP7, GZMH, HERPUD1, and MAP2K1) as a vitiligo‐gene signature (VGS)." (PMID 40974370, 2025).
Yersinia infection (1 paper, 2025). "However, those with a normal BMI should be cautious to prevent Yersinia infection, since MAP2K1, PLCG1, and MYD88 exhibit mutual exclusivity and are significantly enriched in this pathway." (PMID 40768543, 2025).